PWWP2B (PWWP domain containing 2B)
Description:
Chromatin-binding protein that acts as an adapter between distinct nucleosome components (H3K36me3 or H2A.Z) and chromatin-modifying complexes, contributing to the regulation of the levels of histone acetylation at actively transcribed genes. Competes with CHD4 and MBD3 for interaction with MTA1 to form a NuRD subcomplex, preventing the formation of full NuRD complex (containing CHD4 and MBD3), leading to recruitment of HDACs to gene promoters resulting in turn in the deacetylation of nearby H3K27 and H2A.Z. Plays a role in facilitating transcriptional elongation through regulation of histone acetylation (By similarity). Negatively regulates brown adipocyte thermogenesis by interacting with and stabilizing HDAC1 at the UCP1 gene promoter, thereby promoting histone deacetylation at the promoter leading to the repression of UCP1 expression (By similarity).
Synonyms: PWWP2; bA432J24.1; FLJ46823; pp8607
Tractability: No criterion of Open Targets' tractability assessment is met for any kind of drug.
Gene: Protein-coding gene on chromosome 10 (132,397,168 to 132,417,859, forward strand). Ensembl gene ENSG00000171813.
Subcellular location (Human Protein Atlas): Nucleoplasm
Pathways (Reactome):
Chromatin organization: NuRD complex assembly
Gene Ontology:
Molecular function: NuRD complex binding; protein binding
Biological process: chromatin remodeling; positive regulation of transcription elongation by RNA polymerase II; regulation of cold-induced thermogenesis
Cellular component: nucleoplasm; nucleus
Genetic constraint (gnomAD): Loss-of-function variants: 9 observed, 8.8 expected, observed/expected ratio (o/e) 1.02, 90% interval 0.61 to 1.71. That is too few expected variants to judge how well the gene tolerates losing a copy. Missense variants: 831 observed, 786.37 expected, observed/expected ratio (o/e) 1.06, 90% interval 1 to 1.12. Synonymous variants: 459 observed, 365.53 expected, observed/expected ratio (o/e) 1.26, 90% interval 1.16 to 1.36.
Homologues: Orthologues: chimpanzee PWWP2B (99% identical), macaque LRRC27 (90% identical), mouse Pwwp2b (79% identical), rat Pwwp2b (79% identical), pig PWWP2B (76% identical), guinea pig PWWP2B (75% identical), dog PWWP2B (75% identical), tropical clawed frog pwwp2b (53% identical), zebrafish pwwp2b (49% identical). Paralogues in human: PWWP2A (34% identical), DNMT3A (16% identical), DNMT3B (14% identical), DNMT3L (7% identical).
Diseases named in the same sentence as PWWP2B in open-access papers:
PWWP2B is named in the same sentence as 5 diseases in open-access papers, as found by Europe PMC text mining. Sharing a sentence is not in itself a finding about the gene and the disease. The quoted sentences say what the papers report.
gastric cancer (1 paper, 2021). A primary or metastatic malignant neoplasm involving the stomach. "The HAP1 cell line was used to determine how the loss-of-function of RNF43 or PWWP2B correlate with gastric cancer." (PMID 34149925, 2021). "In addition, we found RNF43 and PWWP2B mutations in 7 and 6 of 34 gastric cancer patients, respectively." (PMID 34149925, 2021). "Our data demonstrated that RNF43 and PWWP2B are a biomarker that predict recurrence of gastric cancer." (PMID 34149925, 2021). "RNA sequencing data reveals that RNF43 and PWWP2B expression were down-regulated in recurrence gastric cancer patients." (PMID 34149925, 2021). "In this study, we applied an RNA sequencing (RNA-seq) approach to identify RNF43 (i.e., verify a known marker) and PWWP2B (i.e., explore a novel marker) genes differentially expressed in gastric cancer and adjacent normal tissues from 34 patients." (PMID 34149925, 2021). "The RNF43 and PWWP2B genes are potential biomarkers candidates for patients with advanced gastric cancer." (PMID 34149925, 2021). "RNF43 and PWWP2B genes were weakly expressed in MKN45 cells compared with the other gastric cancer cell types." (PMID 34149925, 2021). "In summary, the results of this study indicate that RNF43 and PWWP2B are downregulation in gastric cancers compared with normal adjacent gastric mucosa." (PMID 34149925, 2021). "Next, we investigated the anti-cancer effects of selected drugs in RNF43 and PWWP2B down-regulated MKN45 gastric cancer cells and xenograft model." (PMID 34149925, 2021). "PWWP2B was chosen because it is a gene which is downregulated in gastric cancer." (PMID 34149925, 2021). "As far as we know, the RNF43 gene is well known to be associated with gastric cancer, but the PWWP2B gene has not been found to be associated with gastric cancer." (PMID 34149925, 2021). "Especially, PWWP2B KO cell line formed colonies much larger than WT and RNF43 KO cells, suggesting that the PWWP2B KO might endow gastric cancer cells with accelerated proliferative capability." (PMID 34149925, 2021). "Therefore, anti-cancer effects of selected drugs were re-tested in RNF43 and PWWP2B down-regulated MKN45 gastric cancer xenograft model." (PMID 34149925, 2021). "At the 3-year follow-up 11 of 34 patients (32%) had gastric cancer relapse (11 of 11 [100%] in the low RNF43 and low PWWP2B expression group)." (PMID 34149925, 2021). "We to try select effective drugs in recurrence gastric cancer patients with low RNF43 and low PWWP2B expression, by using HAP1 cell line." (PMID 34149925, 2021). "Using a gastric cancer cohort, we retrospectively evaluated the relationship between RNF43 and PWWP2B expression levels and clinical characteristics." (PMID 34149925, 2021). "We found that gastric cancer recurrence patients showed downregulated RNF43 and PWWP2B (100%)." (PMID 34149925, 2021). "Therefore, in this study, 1,449 FDA-approved drugs were screened to determine whether they could be used as therapeutic agents for the treatment of gastric cancer using growth inhibition assays of HAP1, HAP1 RNF43 KO, and HAP1 PWWP2B KO cells." (PMID 34149925, 2021).
mastitis (1 paper, 2024). Inflammation of breast tissue during lactation or postpartum due to an obstructed duct or infection. "The same region partially overlaps the CNVR_1549_P (the region comprising the JAKMIP3, DPYSL4, STK32C, LRRC27, PWWP2B) resulted associated with clinical mastitis in Mexican Holstein Cattle." (PMID 38771855, 2024).
Obesity (1 paper, 2021). Accumulation of substantial excess body fat. "Ablation of Pwwp2b promotes adipocyte thermogenesis and ameliorates diet‐induced obesity in vivo." (PMID 34180153, 2021).
cancer (3 papers, 2020 to 2021). A tumor composed of atypical neoplastic, often pleomorphic cells that invade other tissues. "To identify Food and Drug Administration (FDA)-approved drugs that selectively target cancer cells with inactivated RNF43 and PWWP2B genes, we performed a high-throughput screening of 1,449 drugs in HAP1, HAP1 RNF43 KO, and HAP1 PWWP2B KO cells." (PMID 34149925, 2021). "By comparing the transcriptome sequences of the cancer tissues with their matched normal tissues, we identified differentially expressed genes, including RNF43 and PWWP2B." (PMID 34149925, 2021). "Importantly, based on our preclinical finding, docetaxel trihydrate, pelitinib, and uprosertib have significant anti-cancer effects in cancers with low RNF43 and PWWP2B expression (HAP1 RNF43 KO, HAP1 PWWP2B KO cells, MKN45 cells, and KMN45 xenografts)." (PMID 34149925, 2021).
tumor (1 paper, 2021). "Furthermore, a correlation between low RNF43 and PWWP2B expression and tumor recurrence was seen." (PMID 34149925, 2021).